ADAMTS12 (ADAM metallopeptidase with thrombospondin type 1 motif 12)
Diseases named in the same sentence as ADAMTS12 in open-access papers (continued):
Sharing a sentence is not in itself a finding about the gene and the disease.
Arthritis (7 papers, 2011 to 2023). Inflammation of a joint. "Among them, the association of ADAMTS-12 with arthritis and osteoarthritis has been described in several studies along with other members of the ADAMTS family such as ADAMTS-7, and the aggrecanases ADAMTS-4 and ADAMTS-5." (PMID 33996918, 2021). "ADAMTS-12-deficient mice model with arthritis are critical for verifying its role in the course of both osteoarthritis and rheumatoid arthritis in vivo." (PMID 24876675, 2014). "For instance, ADAMTS-12 has been proven to be associated with the pathogenesis of arthritis, intervertebral disc degeneration, inflammation, and invasion and metastasis of tumor." (PMID 24876675, 2014). "Criteria were set as a 1.5-fold change threshold in the CAIA severity change and three genes were found including collagen triple-helix repeat-containing 1 (Cthrc1), C1q and TNF-related protein 3 (C1qtnf3), and ADAMTS-12, which were all associated with both gender and arthritis." (PMID 24876675, 2014). "The role of ADAMTS-7 and ADAMTS-12 in the pathogenesis of arthritis was firstly supported by their ability to cleave COMP." (PMID 37651409, 2023). "Pathologically, the upregulation of ADAMTS12 expression and cleavage of COMP by ADAMTS12 has been demonstrated in arthritis." (PMID 34093655, 2021). "In accordance with this concept, recent studies show that ADAMTS-12 also plays a critical role in the pathological process of arthritis." (PMID 24876675, 2014). "Furthermore, participation of ADAMTS-12 in arthritis or in neuronal disorders has also been suggested through degradation of components of the extracellular matrix." (PMID 33996918, 2021). "Overall, ADAMTS-12 has an essential role in the progression of arthritis and may serve as a therapeutic target for arthritis treatments." (PMID 26696755, 2015). "Collectively, these genetic and in vitro studies indicate that ADAMTS-12 plays an important role in the pathogenesis of arthritis and may be a potential target for developing new treatments for arthritis." (PMID 24876675, 2014). "Abnormal level and/or function of ADAMTS-12 may induce dysregulation of cartilage, which finally leads to arthritis." (PMID 24876675, 2014). "It was approved that ADAMTS-12, COMP, aggrecan, GEP, α2 M, and TNF-α constitute an interplay and interaction network in mediating cartilage degradation in arthritis." (PMID 24876675, 2014). "In addition, ADAMTS-12 also played a critical role in the pathogenesis of arthritis since ADAMTS-7 and ADAMTS-12 share the common substrate (COMP)." (PMID 26696755, 2015). "In addition, the cartilage oligomeric matrix protein (COMP)-processing activities of ADAMTS7 and ADAMTS12 were inhibited by α2M, suggesting that dysregulation of the ADAMTS7 and ADAMTS12 protease activity through α2M could be involved in arthritis." (PMID 34268335, 2021). "ADAMTS-12 is a member of a disintegrin and metalloproteinase with thrombospondin motifs (ADAMTS) family of proteases, which were known to play important roles in various biological and pathological processes, such as development, angiogenesis, inflammation, cancer, arthritis, and atherosclerosis." (PMID 24876675, 2014).
colon cancer (7 papers, 2014 to 2025). "The aberrant methylation of ADAMTS12, as a novel tumor suppressor gene, has been previously investigated only in colon cancer, which was associated with disease progression." (PMID 34198725, 2021). "ADAMTS-12 has been specifically detected in activated fibroblasts in the proximity of colon cancer cells." (PMID 33996918, 2021). "ADAMTS12 is also highly expressed in esophageal squamous cell carcinoma but has low expression in colon cancer." (PMID 32884571, 2020). "ADAMTS-12 is mainly produced by stromal cells at the earliest stages not only of breast tumors but also of colon cancer." (PMID 28099917, 2017). "The expression of ADAMTS-12 was doubled when fibroblasts coculture with colon cancer cells compared with fibroblasts cultures alone." (PMID 24876675, 2014). "Finally, the stromal cells surrounding the colon cancer cells were found to be responsible for the increased expression of ADAMTS12." (PMID 39940703, 2025). "Furthermore, in colon tumors there is a dual regulation of ADAMTS-12 expression: first, an epigenetic inactivation in colon cancer cells due to high levels of methylation of ADAMTS12 promoter." (PMID 33996918, 2021). "Promoter methylation was found to be elevated in the tumor material compared with normal tissue; in addition, RT-qPCR amplification showed no significant ADAMTS12 expression in selected microsatellite-stabilized colon cancer cell lines." (PMID 39940703, 2025).
lung adenocarcinoma (5 papers, 2020 to 2025). A carcinoma that arises from the lung and is characterized by the presence of malignant glandular epithelial cells. "This analysis would indicate that patients with lung adenocarcinoma in which truncating mutations in the ADAMTS12 gene were detected, would have a worse prognosis than those with the unaltered gene." (PMID 33996918, 2021). "We use topological data analysis to leverage this observation and uncover 38 elusive candidate cancer-associated genes, including inactivating mutations of the metalloproteinase ADAMTS12 in lung adenocarcinoma." (PMID 32732999, 2020). "Immunodeficient mice injected with A549 lung adenocarcinoma (LUAD) cells overexpressing ADAMTS12 had a deficiency of tumor growth in comparison with tumors formed from parental A549 cells." (PMID 32732999, 2020). "Among the less studied, elusive candidate cancer-associated mutations identified with our approach, we have studied the inactivating mutations of ADAMTS12 occurring in lung adenocarcinoma." (PMID 32732999, 2020). "Patients with lung adenocarcinoma with the ADAMTS12 mutation would have a worse prognosis." (PMID 34970479, 2021). "In the group of patients with lung adenocarcinoma, significant differences in ADAMTS12 promoter methylation were noted with regard to cigarette smoking and ethnic origin." (PMID 39940703, 2025). "ADAMTS-12 overexpression in A549 lung adenocarcinoma cells inhibits subcutaneous tumor formation in immunodeficient SCID mice in comparison with animals injected with A549 parental cells." (PMID 33996918, 2021).
Stroke (5 papers, 2020 to 2023). Sudden impairment of blood flow to a part of the brain due to occlusion or rupture of an artery to the brain. "These variants were genotyped within a cohort of 270 affected offspring trios, association analysis revealed the ADAMTS12 variant rs77581578 to be significantly under-transmitted (p = 6.26x10-3) to pediatric stroke patients." (PMID 32817637, 2020). "Further evidence that ADAMTS12 could display a role in pediatric stroke was obtained through the sequencing and fine mapping of ADAMTS12 gene variants." (PMID 33996918, 2021). "Interestingly, the ADAMTS12 variant rs1364044 has recently shown to be associated with the pathogenesis of cerebral aneurysms emphasizing the role of the gene in stroke related phenotypes." (PMID 32817637, 2020). "Further functional studies are warranted to assess the functional role of ADAMTS12 in the pathogenesis of stroke." (PMID 32817637, 2020). "Recently, we have reported results of a family-based genome wide association study (GWAS) for pediatric stroke pointing our attention to ADAMTS2 and ADAMTS12." (PMID 32817637, 2020). "Our findings point on ADAMTS12 as a promising new candidate gene for pediatric stroke hence we focused on this gene for a subsequent fine mapping analysis to refine the identified association signal." (PMID 32817637, 2020). "Here, we provide further evidence for ADAMTS12 to likely play a role in pediatric stroke." (PMID 32817637, 2020). "However, the ADAMTS12-COMP-thrombin axis has not yet been reported in the context of (pediatric) stroke." (PMID 32817637, 2020).
osteoarthritis (4 papers, 2014 to 2023). A noninflammatory degenerative joint disease occurring chiefly in older persons, characterized by degeneration of the articular cartilage, hypertrophy of bone at the margins and changes in the synovial membrane. "Additional finding linking ADAMTS-12 with osteoarthritis pathologies came from the identification of ADAMTS12 polymorphisms associated with RA." (PMID 33996918, 2021). "Further confirmation of ADAMTS-12 participation in osteoarthritis processes was recently demonstrated through the employment of an in vivo collagen-induced arthritis (CIA) model by using Adamts12 deficient mice." (PMID 33996918, 2021). "ADAMTS-12's involvements in osteoarthritis is most probably due to its association and degradation of cartilage oligomeric matrix protein (COMP)." (PMID 24876675, 2014). "Since its first annotation in the human genome 20 years ago (NCBI Gene ID: 81792), ADAMTS-12 has been associated to different biological processes in both physiological and pathological conditions, including development, cancer, osteoarthritis, neurological disorders and inflammation." (PMID 33996918, 2021). "The cited authors showed that ADAMTS group enzymes, namely ADAMTS7 and ADAMTS12, are overexpressed in cartilage and synovial membrane in osteoarthritis patients, contributing to COMP degradation." (PMID 36079004, 2022). "ADAMTS-12 participates in different processes related to an inflammatory response such as asthma, colitis, sepsis, pancreatitis and osteoarthritis." (PMID 33996918, 2021). "This in vitro data provide insight into the critical role of ADAMTS-12 in the initiation and progression of osteoarthritis which needs to be further confirmed using in vivo genetically modified animal models." (PMID 24876675, 2014). "For instance, ADAMTS-7 mRNA is found to be significantly increased in the cartilage of patients with rheumatoid arthritis (RA) and only slightly increased in the cartilage of patients with osteoarthritis (OA), whereas ADAMTS-12 mRNA is significantly increased in both OA and RA cartilage." (PMID 24876675, 2014). "In fact, ADAMTS-12 participation in arthritic processes has been mainly related to its ability to degrade COMP because fragments generated following its cleavage were found in diseased cartilage, synovial fluid and in serum of patients with knee injuries, osteoarthritis and rheumatoid arthritis." (PMID 33996918, 2021).
Alzheimer disease (3 papers, 2015 to 2020). A progressive, neurodegenerative disease characterized by loss of function and death of nerve cells in several areas of the brain leading to loss of cognitive function such as memory and language. "As well, another top gene (ADAMTS12) is also implicated in control of immune responses and angiogenesis, deregulated in course of Alzheimer’s disease." (PMID 26379234, 2015).
bladder cancer (3 papers, 2022 to 2025). "Subsequently, we verified the effects of LINC01929, miR-6875-5p and ADAMTS12 on the invasive function of bladder cancer cells through a series of functional experiments." (PMID 35646642, 2022). "The current data suggest that ADAMTS12 is differentially expressed in advanced bladder cancer compared to normal tissues." (PMID 35646642, 2022). "Our findings provide an elucidation of the molecular mechanism by which advanced bladder cancer highly expressed LINC01929 upregulates ADAMTS12 expression through competitive adsorption of miR-6875-5p." (PMID 35646642, 2022). "However, the precise mechanism of action of ADAMTS12 in bladder cancer remains elusive, necessitating further research." (PMID 39761856, 2025). "It has been reported that LINC01929, which is highly expressed in advanced bladder cancer, upregulates the expression level of ADAMTS12 through competitive adsorption of miR-6875-5p, and based on this molecular mechanism, overexpressed miR-6875-5p inhibits the progression of bladder cancer." (PMID 36204659, 2022). "Functionally, ADAMTS12 knockdown inhibited the progression of bladder cancer." (PMID 35646642, 2022). "Therefore, we selected ADAMTS12 for further in vitro functional assays to verify whether it has an effect on the progression and invasion of bladder cancer." (PMID 35646642, 2022).
ischemic stroke (3 papers, 2020 to 2023). A stroke disorder caused by obstruction of blood flow to the brain, due to thrombotic (local blood clot formation) or embolic (due to a blood clot or other material traveling from another site) event. "For example, an increase in ADAMTS12 activity would hypothetically lead to less inhibition of thrombin and an elevated risk for ischemic stroke." (PMID 34065604, 2021). "An increase in ADAMTS12 activity would hypothetical lead to the degradation of COMP resulting in less inhibition of thrombin and an elevated risk for ischemic stroke." (PMID 32817637, 2020). "Interestingly, most of the top 10 upregulated DEGs, such as Thbs1, CD36, ITGA4, and ADAMTS12, are involved in the function of endothelial cells, as shown in the heatmap, implying a role of NeuroD1 in regulating the gene expression of endothelial cells post ischemic stroke." (PMID 38270116, 2023).
pancreatic adenocarcinoma (3 papers, 2022 to 2025). "In contrast, no such difference was noted in an integrated pan-cancer analysis of the ADAMTS12 gene, directed mainly against pancreatic adenocarcinoma." (PMID 39940703, 2025).
schizophrenia (3 papers, 2014 to 2021). A major psychotic disorder characterized by abnormalities in the perception or expression of reality. "The evidence in the literature seems to support this link between neurocan and ADAMTS-12, since they are also associated with certain brain disorders such as schizophrenia and bipolar disorder (at least in the case of ADAMTS-12, also with narcolepsy)." (PMID 32150898, 2020). "The ADAMTS-12 gene had been shown to be a functional and positional candidate in the susceptibility of schizophrenia by mutation analysis in Puerto Rican patients of Spanish descent." (PMID 24876675, 2014). "Furthermore, in support of previous observations, by different genomic approximations the ADAMTS-12 locus has been associated with several human pathologies like asthma, schizophrenia or predisposition to pediatric stroke." (PMID 33996918, 2021). "Recently ADAMTS-12 was also reported to have an association with schizophrenia." (PMID 24876675, 2014). "Therefore, ADAMTS-12 can be considered an important player in mediating and resolving the inflammatory response and, its absence may result in pathologies known to be due in part to a not well resolved inflammatory process like can be the case of schizophrenia." (PMID 33996918, 2021).
asthma (2 papers, 2014 to 2021). "Above all, ADAMTS-12 has a genetic linkage with asthma and a deficiency in ADAMTS-12 leads to defects in both the normal and hyperresponsive inflammatory response." (PMID 24876675, 2014). "Thus, in the human genome screening program ADAMTS12 was identified as a putative asthma associated gene." (PMID 33996918, 2021). "ADAMTS-12 has been identified as one asthma-associated gene in the human genome screening program." (PMID 24876675, 2014). "In addition, variation of ADAMTS-12 was also associated with asthma in the outbred Germans." (PMID 24876675, 2014). "Recently, asthma OVA and HDM model were generated in the ADAMTS-12-deficient mice to determine the role of ADAMTS-12 in this disease." (PMID 24876675, 2014). "Furthermore, there was a significant difference between asthma cases and controls in the frequencies of long range haplotypes composed of SNPs at ADAMTS-12." (PMID 24876675, 2014). "ADAMTS-12 also participates in other pathological situations in which a common trail of an inflammatory outburst is present such as the allergen-induced hyperresponsiveness detected in asthma or the extracellular matrix degradation observed in osteoarthritic processes." (PMID 33996918, 2021).
atherosclerosis (2 papers, 2014 to 2025). A disease characterized by the build-up of fatty material and calcium deposition in the arterial wall resulting in partial or complete occlusion of the arterial lumen. "The physiological roles of the metalloprotease-proteoglycan ADAMTS7, a drug target in atherosclerosis and vascular restenosis, and its homolog ADAMTS12, are undefined in the cardiovascular system." (PMID 40115634, 2025). "Motivated by the significance of ADAMTS7 in atherosclerosis, where it is now a drug target, and observation of overlapping expression in developing and adult heart valves, we investigated the role of ADAMTS7 and ADAMTS12 in cardiac valve ECM." (PMID 40115634, 2025).
breast tumor (2 papers, 2014 to 2017). "In this scenario and in the absence of fibulin-2, ADAMTS-12 could contribute to tumor progression by increasing the migratory capacity of breast tumor cells on collagen-1." (PMID 24457941, 2014).